CTLA4 (cytotoxic T-lymphocyte associated protein 4)
Diseases named in the same sentence as CTLA4 in open-access papers (continued):
Sharing a sentence is not in itself a finding about the gene and the disease.
melanoma (continued). "In 2011, the US Food and Drug Administration (FDA) approved the first checkpoint-blocking antibody Yervoy, an anti-CTLA-4 antibody, for the treatment of patients with advanced melanoma." (PMID 32793247, 2018). "A phase I trial of nivolumab (anti-PD-1) and ipilimumab (anti-CTLA-4) combination on patients with advanced melanoma produced an unprecedented 53% objective response rate (ORR), leading to two-year overall survival (OS) in 79% of cases (NCT01927419)." (PMID 30191140, 2018). "Treatment with the anti-CTLA-4 drug ipilimumab, was shown to heighten T cell infiltration into melanomas and to broaden the TIL response to these tumors." (PMID 30285902, 2018). "The CTLA-4 inhibitor ipilimumab which is FDA approved for treatment of stage IV melanoma is an IgG1 antibody while tremelimumab is IgG2." (PMID 30227886, 2018). "For example, it has been demonstrated that an increased frequency of blood-circulating ICOS+ CD4+ T cells, sustained over a period of 12 weeks of anti-CTLA-4 therapy, correlates with favorable clinical outcome in melanoma patients." (PMID 29494517, 2018). "The Checkmate 067 trial demonstrated that anti-PD-1 and anti-CTLA-4 either alone or in combination imparted increased survival in untreated melanoma." (PMID 30568917, 2018). "Accordingly, treatment with a-CTLA4-TGFβRII also resulted in higher tumor-reactive IFN-γ-expressing CD8+ cells compared to treatment with a-CTLA-4 in mice bearing human melanoma PDX." (PMID 29467463, 2018). "Following the approval of BRAF/MEK inhibitors and PD-1/CTLA-4 blocking antibodies starting in 2011, the use of HD IL-2 in the frontline therapy of melanoma gradually declined." (PMID 28923120, 2017). "In a murine melanoma vaccine model, inhibition of both CTLA-4 or PD-1 increased the proportion of CTLA-4 and PD-1-expressing CD4/CD8 tumor infiltrating T effector cells and decreased intratumoral T regulatory cells, as compared to either agent alone." (PMID 28420805, 2017). "Combined inhibition of IDO and immune checkpoint blockade (CTLA-4, PD-1, and PD-L1) has shown T cell dependent synergy in melanoma and breast cancer mouse models." (PMID 28239469, 2017). "Anti-CTLA-4 and anti-PD-1 combination therapy has already demonstrated improved clinical response rates in melanoma compared to either agent alone." (PMID 29211042, 2017). "Based on the success of dual immunotherapy combinations in melanoma, PD-1 inhibitors have been combined with the CTLA-4 inhibitor, ipilimumab." (PMID 28428947, 2017). "Immune checkpoint inhibitors such as the anti-CTLA-4 antibody Ipilimumab or the anti-PD-1 antibody Nivolumab or Pembrolizumab have been FDA-approved for treatment of melanoma and non-small cell lung cancer (NSCLC)." (PMID 29157287, 2017). "In 2011, the first immune checkpoint inhibitor (ipilimumab as an anti-CTLA-4 antibody) was approved by the FDA as for the treatment of melanoma that crated a footstep in immunotherapy cancer treatment." (PMID 28878676, 2017). "The development of several new systemic treatment options including, BRAF and MEK as well as CTLA-4 and PD-1 targeting immune checkpoint inhibitors have revolutionized the daily practice of melanoma treatment." (PMID 28374234, 2017). "For example, patients with advanced melanoma show a response rate of 11% with ipilimumab (anti-CTLA-4), which is increased up to 61% when treated in combination with nivolumab (anti-PD-1)." (PMID 28611299, 2017). "We performed a meta-analysis for OS with anti-CTLA-4 including 2 studies enrolling patients with melanoma treated with ipilimumab." (PMID 29245905, 2017). "There are ongoing trials evaluating the dual CTLA-4 and PD-1 inhibition therapy in melanoma patients with brain metastases (NCT02320058, NCT02621515)." (PMID 28993799, 2017). "Another group also explored the triplet combination of RT, CTLA-4 inhibition, and PD-L1 in a melanoma mouse model [38•]." (PMID 28344743, 2017).
melanoma (continued). "Targeting co-inhibitory receptors or immune checkpoints such as PD-1 and CTLA-4 by antibody blockade, alone or in combination, is now an established strategy for treating patients with melanoma and non-small cell lung cancer." (PMID 29228684, 2017). "The combination of an anti-PD-1 and an anti-CTLA-4 antibody was more effective than the individual monotherapies in advanced melanoma." (PMID 28703774, 2017). "In the clinical context, blocking PD-L1/PD-1 interaction with pembrolizumab is more effective than blocking CTLA-4 with ipilimumab in the treatment of advanced melanoma." (PMID 28611299, 2017). "They found that while tumors responded to RT and anti-CTLA4, resistance remained common due to upregulation of PD-L1 on melanoma cells." (PMID 28344743, 2017). "Ipilimumab and tremelimumab, two inhibitors to CTLA-4, have shown a promising antitumor activity in patients with malignant melanoma." (PMID 29209232, 2017). "Tremelimumab is an antibody that blocks CTLA-4 and demonstrates clinical efficacy in a subset of advanced melanoma patients." (PMID 28807052, 2017). "CTLA-4 blockage was first tested in melanoma cases with an anti-CTLA-4 inhibitory molecule ipilimumab." (PMID 28848761, 2017). "CTLA4 is expressed on T cells acting as a negative regulator and inhibiting host immune response to melanoma." (PMID 27776349, 2017). "Ipilimumab, an anti-CTLA4 antibody, and nivolumab and pembrolizumab, antibodies directed against PD-1, have demonstrated significant clinical activity in advanced melanoma including improvements in PFS and OS and induction of durable responses." (PMID 28103611, 2017). "For example, some immunological treatments involving CTLA-4 or PD-1/programmed death ligand 1 (PD-L1) receptors have shown good results in melanoma." (PMID 28848246, 2017). "New treatments for melanoma involving the use of targeted agents such as vemurafenib (BrafV600E inhibitor) and ipilimumab (anti-CTLA4) are cost-prohibitive in many low- to middle-income countries." (PMID 28562344, 2017). "Immune checkpoint inhibitors targeting CTLA-4, PD-1, and PD-L1 have shown clinical benefit in patients with advanced melanoma, non-small-cell lung cancer, and several other cancers." (PMID 28845161, 2017). "Targeting the immune checkpoint molecules CTLA-4, PD-1 and PD-L1 is completely revolutionizing the treatment of advanced melanoma." (PMID 28231855, 2017). "Antibodies that blockade the functions of PD-1, PD-L1 and CTLA-4 have all been approved as melanoma therapeutics within the last 5 years." (PMID 29137331, 2017). "Phase I/II trials examining antibodies targeting another checkpoint inhibitor, cytotoxic T-lymphocyte-associated protein 4 (CTLA-4), (with e.g., ipilimumab, an FDA approved immunotherapy drug for melanoma) are also ongoing." (PMID 28640192, 2017). "Our study demonstrates that pretreatment expression of a signature of 15 genes derived from whole blood samples obtained from patients with stage IV melanoma can predict for response to a CTLA-4 inhibitor." (PMID 28807052, 2017). "A phase Ib study using T-VEC with ipilimumab, an anti-CTLA-4 antagonist Ab, in patients with unresectable stage IIIb/IV melanoma has been recently reported." (PMID 28555136, 2017). "In this regard, ISF35 in combination with anti-CTLA-4 and anti-PD-1 checkpoint antibodies shows a promising therapeutic efficacy against melanoma in the brain." (PMID 29129918, 2017). "The potential for additional clinical activity with CTLA-4 blockade has been shown with both GM-CSF and interferon-α in patients with advanced melanoma." (PMID 28239469, 2017). "The life-threatening side effects should disable the anti-CTLA-4 antibodies as more suitable therapeutic ICI targeting antibodies for the treatment of patients with advanced melanoma than anti-PD-1 antibodies." (PMID 29137370, 2017).
melanoma (continued). "In melanoma patients treated with tremelimumab, an IgG2 antibody that targets CTLA-4 on T cells, a genomic signature predictive of prolonged survival has been recently identified, consisting of four gene transcripts." (PMID 28331613, 2017). "OS curves plateaued after 3 years - akin to the pattern observed in the pooled analyses of melanoma patients treated with CTLA-4 inhibitor ipilimumab and PD-1 inhibitors nivolumab and pembrolizumab, albeit at a lower fraction." (PMID 28923120, 2017). "A 47-year-old female with recurrent BRAF mutant positive melanoma received combination anti-PD-1 and anti-CTLA-4." (PMID 28239462, 2017). "Most reports document isolated cases of interstitial nephritis with specific agents and regimens, such as anti-PD-1 monotherapy, and combination anti-CTLA-4/PD-1 treatment, in melanoma." (PMID 29162153, 2017). "Various treatment strategies have received US Food and Drug Administration (FDA) approval including cell vaccination for prostate cancer as well as immune checkpoint inhibition targeting the CTLA-4 or the PD-1/PD-L1 axis in melanoma, lung, and kidney cancer." (PMID 28331613, 2017). "More recently, combined radiation and CTLA-4 blockade showed potential synergy in advanced melanoma patients." (PMID 28239469, 2017). "Here, we applied this model to advanced melanoma patients receiving chemotherapy (n = 116) or anti-CTLA-4 therapy (n = 128)." (PMID 29108362, 2017). "Drugs that mediate ICB by targeting the inhibitory receptors CTLA-4 and PD-1 (Figure 2inset panel) have been shown to induce durable responses in subsets of patients with various types of cancer including melanoma, NSCLC, and renal cell cancer (RCC)." (PMID 29276510, 2017). "In vivo AR42 or sodium valproate enhanced the anti-tumor efficacy of anti-PD-1 and of anti-CTLA4 antibodies in the B16 melanoma model." (PMID 29137331, 2017). "IFN-α2b efficacy is increased by administering anti-CTLA4 antibody to patients with unresectable melanoma (NC01708941) and the combination treatment utilizing Peg-IFN-α2b and the anti-PD-1 pembrolizumab are currently in clinical trials." (PMID 28798748, 2017). "Functional studies are also required to define the mechanisms of action of CTLA-4 gene variants on both Teff cells and tumor cells in IPI-treated melanoma patients." (PMID 28446908, 2017). "Intriguingly, the efficacy of anti-CTLA-4 in mouse melanoma models depended on the microbiota of these mice, raising the important question of how the microbiota affects immunometabolism." (PMID 29250078, 2017). "It is noticeable that in our murine melanoma model, anti-PD-L1 treatment is less effective than anti-CTLA-4 treatment even in wild-type mice." (PMID 28611299, 2017). "Here, the authors demonstrate that B2M loss is a mechanism of primary and acquired resistance to therapies targeting CTLA4 or PD-1 in melanoma patients." (PMID 29070816, 2017). "Upregulation and sustained coexpression of coinhibitory receptors is regarded as the hallmark of CTL exhaustion; immune checkpoint blockade targeting CTLA-4 and/or PD-1/PD-L1 has achieved considerable success in the treatment of melanoma and other cancers." (PMID 29033936, 2017). "The anti-CTLA-4 antibody, ipilimumab, has shown durable anti-tumor activities and prolonged survival in participants with advanced melanoma, resulting in its Food and Drug Administration (FDA) approval in 2011." (PMID 28878676, 2017). "In 2011, the United States Food and Drug Administration (FDA) approved the use of ipilimumab, a monoclonal antibody targeted at CTLA-4, for the treatment of melanoma." (PMID 29033936, 2017). "Transient exposure of tumors to pan-HDAC inhibitors opsonized melanoma tumors to the anti-tumor actions of anti-PD-1 and anti-CTLA4 antibodies." (PMID 29137331, 2017).
melanoma (continued). "A decade ago, stage IV melanoma was a death sentence, whereas today, up to half of all stage IV melanoma patients can expect to be cured of their disease through combination anti-CTLA-4 (ipilimumab)/anti-PD-1 (nivolumab or pembrolizumab) checkpoint inhibition." (PMID 28824608, 2017). "Ipilimumab is an anti-CTLA-4 antibody which demonstrated good results when administered to patients with melanoma." (PMID 29213157, 2017). "Currently, few melanoma patients are treated with cytotoxic chemotherapy before receiving CTLA-4 and PD-1 inhibitors." (PMID 28807052, 2017). "The recent advent of inhibitors of immune-checkpoints [cytotoxic T-lymphocyte antigen 4 (CTLA-4) and programmed cell death-1 (PD-1)], and of novel targeted therapies drastically improved survival expectations for advanced melanoma patients." (PMID 29108362, 2017). "Conversely, inhibition of the cholesterol esterification enzyme ACAT-1 was able to improve T cell responses and also improved the efficacy of immune checkpoint blockade by anti-CTLA-4 antibody in a mouse melanoma model." (PMID 29250078, 2017). "Blocking the action CTLA-4 and PD-1 receptors or their ligands by mAbs is effective in treating a number of different tumors including melanoma, NSCLC, bladder cancer, renal cancer, cancers with mismatch repair enzyme deficiency, and Hogkin’s lymphoma." (PMID 28239463, 2017). "Currently, immunotherapies targeting CTLA-4, PD-1, and PD-L1 are approved in a small number of indications, melanoma, bladder, NSCLC, and renal cell carcinoma." (PMID 28420421, 2017). "Other treatments under investigation for some such tumors include the anti–CTLA-4 antibody ipilimumab, an immune-checkpoint-pathway inhibitor that was effective in advanced melanoma." (PMID 27928714, 2017). "The development of antibodies which inhibit CTLA-4 and PD-1 have improved the efficacy of treatment available to patients with stage IV melanoma." (PMID 28807052, 2017). "In other work investigating microbial influences on checkpoint blockade therapy, pretreatment of mice with a cocktail of broad-spectrum antibiotics blocked the efficacy of α-CTLA-4 Ab therapy for established Ret murine melanomas." (PMID 29209327, 2017). "The value of immunotherapy in treating stage IV melanoma became indisputable in 2011, when the U.S. Food and Drug Administration approved ipilimumab, a CTLA-4 inhibitor." (PMID 28807052, 2017). "Ipilimumab (Yervoy), an anti–CTLA-4 agent, was the first monoclonal antibody approved for advanced melanoma and is now also indicated for adjuvant melanoma." (PMID 29928543, 2017). "A recent clinical trial collected biopsies from melanoma patients through checkpoint inhibitor therapy, first before and during anti-CTLA4 therapy and then before and during anti-PD1 therapy." (PMID 28239471, 2017). "Therapeutic strategies to overcome T-cell exhaustion, that is, immune checkpoint blockade, have been developed that target CTLA-4 and PD-1/PD-L1, and these strategies have demonstrated significant efficacy in treating melanoma and non-small-cell lung cancer." (PMID 28474673, 2017). "Since the anti-CTLA4 Ab (ipilimumab) was FDA approved for use in patients with advanced-stage melanoma in 2011, immune checkpoint antagonists (including anti-CTLA4 and anti-PD-1/PD-L1 antibodies) have now been approved for use against six forms of cancer." (PMID 28555136, 2017). "There has been dramatic improvement in survival of patients with advanced melanoma in recent years with the development of modern immunotherapy including cytotoxic T lymphocyte antigen-4 (CTLA-4) inhibitors and programmed death-1 (PD-1) checkpoint inhibitors." (PMID 28993799, 2017). "Pre-existing melanoma antigen-specific antibody response was only studied for CTLA-4 ICI showing a correlation to response." (PMID 29034210, 2017).
melanoma (continued). "We show that inhibition of HSP90 with ganetespib enhances T-cell-mediated killing of patient-derived human melanoma cells by their autologous T cells in vitro and potentiates responses to anti-CTLA4 and anti-PD1 therapy in vivo." (PMID 28878208, 2017). "Blockade of CTLA4 and/or PD-1/PD-L1 have shown clinical successes in melanoma, lung cancer, and other tumor types." (PMID 28586388, 2017). "There is at present an open clinical trial combining the HDAC6 specific HDAC inhibitor ACY-241 with Ipilimumab (anti-CTLA4) and Nivolumab (anti-PD-1) for melanoma (NCT02935790)." (PMID 29137331, 2017). "The CTLA-4-directed mAb Ipilimumab has been approved as first- and second-line therapy for patients with malignant melanoma and showed promising results in terms of overall survival [6, review in 7]." (PMID 27966460, 2017). "Another humanized anti-CTLA-4 antibody, tremelimumab obtained durable responses in phase I/II clinical studies with melanoma but fell short in Phase III randomized clinical trial." (PMID 28536525, 2017). "Both monotherapy and combinatorial approaches with nivolumab (anti-PD-1), pembrolizumab (anti-PD-1), and ipilimumab (anti-CTLA-4) have been promising, with reports of complete and objective responses in as high as 22 and 61% of melanoma patients, respectively." (PMID 29209327, 2017). "In some tumor entities such as melanoma and Hodgkin lymphoma, over all response rates to either single or combined PD-1/CTLA-4 checkpoint inhibition are encouragingly high." (PMID 29312332, 2017). "El fármaco ipilimumab es un anticuerpo anti-CTLA-4 que ha demostrado buenos resultados terapéuticos en pacientes con melanoma." (PMID 29213157, 2017). "ICB, anti-CTLA-4, anti-PD-1, and anti-PD-L1 have been approved for treatment of melanoma and non-small cell lung cancer." (PMID 28465485, 2017). "Comparably to malignant melanoma, a heterogeneous amount of PD-1, Tim-3, CTLA-4, LAG-3, and BTLA were expressed on intratumoral CD8+ T cells from 32 patients with NSCLC." (PMID 28073373, 2017). "Immune inhibitory methods using anti-PD-1 or anti-CTLA-4 monoclonal antibodies have changed the controlling of patients with melanoma." (PMID 28703774, 2017). "This was confirmed in conference papers by others, who show that a TCR diversity score higher than 20% is necessary for good outcome of melanoma patients receiving anti-CTLA-4 antibody treatment." (PMID 28100240, 2017). "In two independent cohorts of melanoma patients treated with anti-CTLA4 and anti-PD1, respectively, we find that B2M LOH is enriched threefold in non-responders (~30%) compared to responders (~10%) and associated with poorer overall survival." (PMID 29070816, 2017). "Melanoma cells express the CTLA-4 and PD-1 immune receptor proteins that are normally expressed in T-cells." (PMID 29872710, 2017). "Immune checkpoint blockade with monoclonal antibodies directed against the inhibitory immune receptors CTLA-4 and PD-1 has emerged as a successful treatment approach for patients with advanced melanoma." (PMID 29213157, 2017). "Monoclonal antibodies targeting the regulatory immune “checkpoint” receptors CTLA-4, PD-1, and PD-L1 are now standard therapy for diverse malignancies including melanoma, lung cancer, and renal cell carcinoma." (PMID 29230210, 2017). "Both antibodies directed against cytotoxic T-lymphocyte-associated protein 4 (CTLA4; ipilimumab) or programmed cell death protein-1 (PD1; nivolumab and pembrolizumab) are approved for use in melanoma patients." (PMID 28955032, 2017). "In melanoma, a tumor that for many years has shown high rate of deaths because of its resistance to standard therapy, administration of both anti-CTLA-4 and anti-PD-1 mAbs significantly increases response rates, PFS and OS of the treated patients." (PMID 29290886, 2017).